ZMIZ1 (zinc finger MIZ-type containing 1)
Description:
Acts as a transcriptional coactivator. Increases ligand-dependent transcriptional activity of AR and promotes AR sumoylation. The stimulation of AR activity is dependent upon sumoylation. Also functions as a transcriptional coactivator in the TGF-beta signaling pathway by increasing the activity of the SMAD3/SMAD4 transcriptional complex. Involved in transcriptional activation of a subset of NOTCH1 target genes including MYC. Involved in thymocyte and T cell development (By similarity). Involved in the regulation of postmitotic positioning of pyramidal neurons in the developing cerebral cortex.
Synonyms: KIAA1224; RAI17; ZIMP10; RP11-519K18.1; FLJ13541; hZIMP10; MIZ; NEDDFSA; TRAFIP10
Tractability: PROTAC: UniProt records ubiquitination sites on it; ubiquitination databases record sites on it; its protein half-life has been measured.
Gene: Protein-coding gene on chromosome 10 (79,068,929 to 79,316,550, forward strand). Ensembl gene ENSG00000108175.
Subcellular location: Nucleus, nucleoplasm; Cytoplasm; Nucleus
Subcellular location (Human Protein Atlas): Nucleoplasm; Cytosol
Gene Ontology:
Molecular function: SMAD binding; transcription coactivator activity; SUMO ligase activity; zinc ion binding
Biological process: androgen receptor signaling pathway; positive regulation of transcription by RNA polymerase II; pyramidal neuron migration to cerebral cortex; SMAD protein signal transduction; transforming growth factor beta receptor signaling pathway; positive regulation of Notch signaling pathway; positive regulation of T cell differentiation; regulation of transcription by RNA polymerase II
Cellular component: cytoplasm; cytosol; nucleoplasm; nucleus; chromatin
Genetic constraint (gnomAD): Loss-of-function variants: 17 observed, 115.71 expected, observed/expected ratio (o/e) 0.15, 90% interval 0.1 to 0.22. The upper end of that interval is the gene's LOEUF score, 0.22, which puts it in group 1 of 6, group 1 being the genes least tolerant of losing a copy. Missense variants: 1,059 observed, 1,498.6 expected, observed/expected ratio (o/e) 0.71, 90% interval 0.67 to 0.74. Synonymous variants: 607 observed, 610.81 expected, observed/expected ratio (o/e) 0.99, 90% interval 0.93 to 1.06.
Gene-disease validity (ClinGen):
ClinGen rates the evidence that ZMIZ1 causes each of these diseases.
complex neurodevelopmental disorder (autosomal dominant): Definitive. A disorder that involves more than one phenotype associated with the central nervous system, including but not limited to intellectual disability, autism, and seizures (epilepsy).
Homologues: Orthologues: chimpanzee ZMIZ1 (100% identical), pig ZMIZ1 (99% identical), dog ZMIZ1 (99% identical), guinea pig ZMIZ1 (99% identical), mouse Zmiz1 (98% identical), rat Zmiz1 (98% identical), rabbit ZMIZ1 (96% identical), macaque ZMIZ1 (92% identical), tropical clawed frog zmiz1 (87% identical), zebrafish zmiz1a (79% identical), zebrafish zmiz1b (48% identical), Drosophila melanogaster tna (36% identical), and 1 more. Paralogues in human: ZMIZ2 (53% identical), PIAS1 (14% identical), PIAS2 (13% identical), PIAS3 (12% identical), PIAS4 (11% identical).
Diseases named in the same sentence as ZMIZ1 in open-access papers:
ZMIZ1 is named in the same sentence as 79 diseases in open-access papers, as found by Europe PMC text mining. Sharing a sentence is not in itself a finding about the gene and the disease. The quoted sentences say what the papers report.
breast carcinoma (11 papers, 2012 to 2025). "Specifically, Prox1 dysregulation is linked to breast cancer progression and metastasis and glioblastoma invasion, while Zmiz1 is associated with breast cancer and prostate cancer." (PMID 38718095, 2024). "Previously, the SNP rs704010 in the ZMIZ1 gene was found to correlate with an increased risk of breast cancer (OR = 1.03) and ER+ BC (OR = 1.02) in women with European ancestry." (PMID 27863437, 2016). "A recent study of patients with breast cancer reported that tumors with increased ZMIZ1 expression were correlated with decreased survival of ESR1-positive breast cancer patients." (PMID 41321316, 2025). "These targets (FGFR2, PTLH, ELL, and ZMIZ1) have already been identified through meta-GWAS of breast cancer." (PMID 40938940, 2025). "In breast cancer, ZMIZ1 enhances ESR1-dependent expression of E2F2, correlating with poor patient outcomes." (PMID 41321319, 2025). "Our results therefore confirmed the ER and ZMIZ1 are within 40 nm of each other, and therefore likely within the same transcriptional complex in breast cancer cell lines." (PMID 38564418, 2024). "Undertaking analysis in ER-positive breast cancer cell line models, we demonstrated a significant change in the ER-mediated transcriptional response on ZMIZ1 knockdown." (PMID 38564418, 2024). "In Latinas, 4 (MAP3K1, ZMIZ1, FGFR2, and TOX3) of the 12 regions have been associated with breast cancer in 1497 cases and 3213 controls." (PMID 27814745, 2016). "Although direct evidence for its ligand-dependent coregulator function with ESR1 in this disease remains limited, studies in ESR1-positive breast cancers have shown that ZMIZ1 participates in the ESR1 chromatin-bound complex to enhance the expression of cell cycle regulators such as E2F2." (PMID 41321319, 2025). "Therefore, we considered the breast cancer specific function of ZMIZ1 to be of key interest for follow-up studies." (PMID 38564418, 2024). "Finally, we show that high ZMIZ1 expression is predictive of worse patient outcome, ER and ZMIZ1 are co-expressed in breast cancer patients in TCGA and METABRIC, and the proteins are co-localised within the nuclei of tumour cell in patient biopsies." (PMID 38564418, 2024). "The SNPs rs10759243 in the KLF4 gene (OR = 1.284, 95% CI, 1.061 – 1.552, p = 0.010) and rs704010 in the ZMIZ1 gene (OR = 1.237, 95% CI, 1.010 – 1.515, p = 0.040) were associated with the risk of clinical stage (UICC) I and II breast cancer compared with normal controls." (PMID 27863437, 2016). "Recent genome-wide association studies of breast cancer have identified eight additional breast cancer susceptibility loci: rs1011970 (9p21, CDKN2A/B), rs10995190 (ZNF365), rs704010 (ZMIZ1), rs2380205 (10p15), rs614367 (11q13), rs1292011 (12q24), rs10771399 (12p11 near PTHLH) and rs865686 (9q31.2)." (PMID 22348646, 2012). "ZMIZ1’s importance in cell growth has been observed in multiple tissues, including decreased growth of MEFs isolated from ZMIZ1-null embryos or siZMIZ1-targeted human dermal lymphatic endothelial cells as well as decreased estrogen-dependent proliferation of siZMIZ1-targeted breast cancer cells." (PMID 41321316, 2025). "ZMIZ1 is coexpressed with ESR1 in breast tumors and enhances the proliferation of breast cancer cells." (PMID 41321316, 2025). "In the breast cancer cell study, interaction between ESR1 and ZMIZ1 to regulate cell cycle progression genes was hypothesized, with demonstrated interactions at the E2F2 gene promoter." (PMID 41321316, 2025). "Given that our qPLEX-RIME data shows a significant enrichment of ZMIZ1 protein vs the control, was undertaken using a breast cancer cell line, and that we did not detect the presence of AR in our qPLEX-RIME data, this implies AR was not within the ER complex in the experimental conditions used." (PMID 38564418, 2024).
prostate carcinoma (8 papers, 2011 to 2025). A carcinoma that arises from epithelial cells of the prostate gland. "Modified ZMIZ1 signaling was associated with various diseases, including vitiligo, multiple sclerosis, leukemia, prostate cancer, and inflammatory bowel disease." (PMID 35372566, 2022). "Our findings raise an interesting question regarding the potential significance of ZMIZ1 effects on AR mediated transcription in prostate cancer pathogenesis and particularly in disease progression during androgen deprivation therapy." (PMID 21949845, 2011). "Further studies into the molecular mechanisms by which ZMIZ1 regulates AR mediated transcription may provide new insight into the biological role of ZMIZ1 in prostate cancer and related human disorders." (PMID 21949845, 2011). "Therefore, it would be interesting to characterize the expression of ZMIZ1 and different length polyQ AR in patient samples of prostate cancer, AIS, and other human disorders that may be closely related to either loss or gain-of-function mutations in the AR gene." (PMID 21949845, 2011). "Here, we assessed the role of ZMIZ1, an AR co-activator, in regulating the activity of the AR with different lengths of polyQ tracts as ARQ9, ARQ24, and ARQ35 in prostate cancer cells." (PMID 21949845, 2011). "Our data confirmed that the treatment of prostate cancer cells with ENZA enhances the effect of radiation through down-regulation of NKX3-1, ZMIZ1, SPDEF and PDE9A genes and up-regulation of LAT, PTPRN2 and OSBPL10 genes in LNCaP cells, as well as up-regulation of CYP1B1 genes in C4-2 cells." (PMID 31221986, 2019). "Expression vectors for the human AR cDNA containing 9, 24, and 35 polyQ tracts and for AR cofactors, including ZMIZ1, ZMIZ2, and ARA70, were co-transfected with an androgen-induced luciferase reporter driven by a 7 Kb PSA promoter-enhancer fragment into prostate cancer cell line, DU145." (PMID 21949845, 2011). "Overall, this was first line of evidence that ZMIZ1, rather than ZMIZ2 or ARA70, enhances the ligand-induced transactivation of AR with shorter polyQ tract in prostate cancer cells." (PMID 21949845, 2011).
Intellectual disability (7 papers, 2021 to 2025). "Pathogenic mutations in ZMIZ1 have been linked to syndromic neural disorders with intellectual disability and neurodevelopmental delay." (PMID 41326741, 2025). "In humans, pathogenic ZMIZ1 mutations have been linked to a syndromic neural disorder with intellectual disability and neurodevelopmental delay." (PMID 40309932, 2025). "In 2019, 19 subjects with intellectual disability and developmental delay were reported carrying variants in ZMIZ1, 2 subjects had a balanced translocation disrupting ZMIZ1 or involving a regulatory region of ZMIZ1." (PMID 40044118, 2025). "The OTUD6B and ZMIZ1 genes were recently identified as causes of syndromic intellectual disability (ID) with shared phenotypes of facial dysmorphism, distal limb anomalies, and seizure disorders." (PMID 34680978, 2021). "Human genetic studies have linked loss-of-function variants in Zinc Finger MIZ-Type Containing 1 (ZMIZ1) to a spectrum of neurodevelopmental disorders (NDDs), such as intellectual disability (ID), autism spectrum disorders (ASD), and attention-deficit/hyperactivity disorder (ADHD)." (PMID 40529245, 2025). "ZMIZ1 is a transcriptional co-activator highly expressed during embryonic brain development in both mice and humans, especially in regions such as the cortex, hippocampus, and cerebellum, areas notably affected in intellectual disability (ID) and autism spectrum disorder (ASD)." (PMID 40529245, 2025).
leukemia (6 papers, 2022 to 2025). A malignant (clonal) hematologic disorder, involving hematopoietic stem cells and characterized by the presence of primitive or atypical myeloid or lymphoid cells in the bone marrow and the blood. "Zmiz1 plays a pivotal role in various biological processes, spanning embryonic development, angiogenesis, immune response, and has been associated with conditions such as cancer, leukemia, and diabetes." (PMID 38686122, 2024). "Knockout of ZMIZ1 inhibited the occurrence of Notch1-induced leukemia, and it was proposed that targeting ZMIZ1 could treat lymphocytic leukemia." (PMID 38866828, 2024). "Similarly, in leukemia, the interaction between ZMIZ1 and Notch1 enhances C-MYC transcription and activity, facilitating leukemia initiation and progression, while ZMIZ1 inhibition attenuates leukemia progression." (PMID 38866828, 2024). "The Zmiz1-Notch1 protein-protein interaction is also of great importance for the normal proliferation of T cell precursors, and disruption of this homoeostasis leads to the development of leukaemia." (PMID 37608097, 2023). "In addition, it is worth to note that ZMIZ proteins have been shown to interact directly with transcription factors (TFs), as is the case for ZMIZ1 in the stimulation of NOTCH-mediated transcription during T-cell development and leukemia." (PMID 39266996, 2024).
multiple sclerosis (6 papers, 2015 to 2024). A progressive autoimmune disorder affecting the central nervous system resulting in demyelination. "Beyond NDDs, Zmiz1 is associated with depression, multiple sclerosis (MS), and Hirschsprung disease (HD)." (PMID 38686122, 2024). "In addition to possible effects on osteogenesis, a region containing ZMIZ1 has been associated with inflammatory/autoimmune diseases including Crohn’s disease and ulcerative colitis, celiac disease, multiple sclerosis, and vitiligo." (PMID 27864696, 2017). "Variants in or near ZMIZ1 have been found to be associated with several complex diseases or traits, including multiple autoimmune diseases (that is, inflammatory bowel disease, multiple sclerosis, celiac disease, vitiligo, Crohn's disease and psoriasis)." (PMID 28447608, 2017). "Several variants in the wider region, independent of the T2D and islet eQTL signal (r2<0.04), have been associated with a variety of autoimmune and inflammatory disorders (including inflammatory bowel disease and multiple sclerosis), in addition to ZMIZ1 expression in immune-relevant monocytes." (PMID 26624892, 2015).
autoimmune disease (5 papers, 2017 to 2025). A disorder resulting from loss of function or tissue destruction of an organ or multiple organs, arising from humoral or cellular immune responses of the individual to their own tissue constituents. "Furthermore, variants in the ZMIZ1 gene have been identified as risk alleles for various human cancers, autoimmune diseases, and chronic inflammation." (PMID 40309932, 2025). "Collectively, our results at the ZMIZ1 locus reveal EBNA2 and autoimmune risk allele-dependent mechanisms possibly underlying the established roles played by genetics and the environment in autoimmune diseases." (PMID 34799401, 2021).
type 2 diabetes (5 papers, 2015 to 2025). "In adipocyte 2, transcription factors associated with neurodegenerative diseases, type 2 diabetes, and cancer (Ctcfl, Etv3, Atf4, Zmiz1, Sp3) showed reduced activity in the old group." (PMID 40631796, 2025). "Beyond reproductive biology, genome-wide association and clinical studies have linked ZMIZ1 variants to autoimmune disease, type 2 diabetes (T2D), and syndromic neurodevelopmental disorders, underscoring its pleiotropic physiological roles." (PMID 41321319, 2025). "Our results suggested that rs12571751 in ZMIZ1 has a significant effect on conferring susceptibility to type 2 diabetes also in the Japanese." (PMID 25951451, 2015). "ZMIZ1 locus has a significant effect on conferring susceptibility to type 2 diabetes also in the Japanese population." (PMID 25951451, 2015). "Among 7 SNPs identified in un-stratified European GWAS meta-analyses, rs12571751 in ZMIZ1 was significantly associated with type 2 diabetes in the present Japanese population, indicating that this locus was common susceptibility locus for type 2 diabetes across different ethnic groups." (PMID 25951451, 2015). "ZMIZ1 has already been identified to be strongly associated with ESRD attributed to type 139 and type 2 diabetes." (PMID 37023747, 2023). "We also constructed GRS-6 by excluding rs12571751 in ZMIZ1 from the GRS-7, and observed that the GRS-6 was associated with type 2 diabetes in the Japanese population (p = 7.9 × 10–3, adjusted for sex, age and BMI)." (PMID 25951451, 2015). "In the present study, we did not observe any association with type 2 diabetes except for ZMIZ1 and KLHDC5 loci in a Japanese population (p ≥ 0.05 adjusted for sex, age and BMI)." (PMID 25951451, 2015).
vitiligo (5 papers, 2016 to 2022). Generalized well circumscribed patches of leukoderma that are generally distributed over symmetric body locations and is due to autoimmune destruction of melanocytes. "Another study confirmed ZMIZ1 as a novel susceptibility locus for vitiligo and further suggested rs1408944 to be the putative causal variant that potentially interrupts TF binding and thus the transcriptional regulation of ZMIZ1." (PMID 26870082, 2016).